IL6 (interleukin 6)
Diseases named in the same sentence as IL6 in open-access papers (continued):
Sharing a sentence is not in itself a finding about the gene and the disease.
psoriasis (continued). "Il-1, Il-6 and TNF-α that mediate psoriasis may alter the hepatocyte function and the arterial smooth muscle cells, which will finally lead to arterial plaque development." (PMID 25713604, 2014). "Immune/inflammatory parameters including IL-6 and IL-22, CLA+ T cells, and Treg lymphocytes may prove to be valuable laboratory tools for the clinical and therapeutic monitoring of psoriasis." (PMID 25136144, 2014). "Altered alpha ketoglutaric acid levels may also play a role within the hyperactive immunogenic state of psoriasis, in which lymphocytes, macrophages, and neutrophils secrete the inflammatory cytokines TNF-α, IL-1, and IL-6." (PMID 25580230, 2014). "A clear increased concentration of IL-1α, TNF-α and IL-6 was found in skin lavage from lesion sites of psoriasis patients, in comparison with skin lavage from non-lesional sites, or from skin of healthy individuals." (PMID 25785188, 2014). "Even though IL-6 is not a central cytokine in psoriasis pathogenesis, it may be a suitable biomarker for assessing treatment outcomes." (PMID 40699767, 2025). "The proportions of pro-inflammatory (TNF-α, IL-6, IL-17, IL-23, and IL-1β) and anti-inflammatory (IL-10) cytokines were assessed in the serum and cutaneous tissue of psoriatic animals produced by IMQ to assess the immunomodulatory impact of ERN in psoriasis-like inflammation." (PMID 40667480, 2025). "These factors include the interleukins, such as IL‐1, IL‐6, and IL‐8, monocyte chemoattractant protein (MCP)‐1, TNF‐α, and granulocyte‐macrophage colony‐stimulating factor (GM‐CSF), which collectively play crucial roles in various inflammatory problems such as atopic dermatitis and psoriasis." (PMID 39968713, 2025). "It is possible that IL-6 is not very important for triggering the inflammatory cascade of psoriasis in the skin environment, but its suppressive effect on regulatory T-cells may explain why this mediator is a more important marker for treatment response." (PMID 37634972, 2024). "Additionally, IDG was shown to inhibit the expression of IL-6, IL-13, IL-17A, TNF-α, and MCP-1, suggesting that IDG may exert its therapeutic effects on psoriasis through its anti-inflammatory properties." (PMID 39465158, 2024). "Here, we investigated the expression of psoriasis-related cytokines (TNF-α, IL-6, IL-22, IL-23, IL-17A, IL-17E, IL-17F, IL-4 and IL-10) in the inflamed skin after mannan exposure at the peak (day 4) and the end (day 7) of psoriasis with/without inhibitor(s) treatment." (PMID 38444844, 2024). "Given that c-Rel deficient DCs are unable to produce inflammatory cytokines including IL-1β and IL-6, we hypothesised that the TLR7/c-Rel signalling axis in DCs regulated the induction of naïve T cells to differentiate into Th17 cells during psoriasis." (PMID 39586195, 2024). "Our findings align with the known functions of IL-6, IL-17, and TNF-α inhibitors, indicating that XYAS, LXJD, and QXAS could significantly reduce IL-6, IL-17, and TNF-α levels and exert an inhibitory effect on epidermal thickening in mice with psoriasis and SDs." (PMID 39411067, 2024). "In the group of psoriasis patients, a negative correlation was found between VMRr and Il-6 or BMI." (PMID 39200092, 2024). "There are no publications yet on the effect of IL-6 on cerebral vessels in patients with psoriasis." (PMID 39200092, 2024). "Strikingly, in recent reports, IL-6/IL6R-mediated STAT3 activation in keratinocytes, rather than in immune cells, was responsible for the development of the psoriatic phenotype in a mouse model, highlighting the localized production and activity of IL-6 as being fundamental in psoriasis development." (PMID 38672088, 2024). "Angiopoietin-like protein 4 (ANGPTL4) is highly expressed in the skin lesions of psoriasis patients, ANGPTL4 recombinant protein promotes psoriasis-like skin lesions in mice, and the knockout of ANGPTL4 inhibits keratinocyte growth and expresses cytokines such as IL-17, IL-6, and TNF-α." (PMID 37762693, 2023).
psoriasis (continued). "Dysfunctional Tregs in peripheral blood of patients with psoriasis have been reported showing that they have a phosphorylation and an aberrant activation of STAT3, which is due to the effects of pro-inflammatory cytokines, not only IL-6, but also IL-21 and IL-23." (PMID 36901778, 2023). "Interestingly, the authors found that a single dose of NF-κB decoy ODN delivered via the combination of IP and the AT1002 analog peptide showed improved therapeutic effects against psoriasis, which significantly suppressed epidermal hyperplasia as well as the production of TNF-α and IL-6 mRNA." (PMID 35335900, 2022). "Functionally, this mechanism resulted in the infiltration of pro‐inflammatory cytokines such as TNF‐α, IL‐1β, IL‐6, IL‐17A, and CXCL‐15, which enhances the inflammatory response in skin lesions and reinforces the cross‐talk between neutrophils and keratinocytes, ultimately aggravating psoriasis." (PMID 35281792, 2022). "In addition, CHALT could also weaken the inflammatory response triggered by IL-6 and JAK/STAT3 signaling pathway in keratinocytes, thereby inhibiting the progression of psoriasis." (PMID 36618400, 2022). "An increased cebpb expression, epidermal thickness, infiltration of dendritic cells, and γδ T cells as well as the expression of pro-inflammatory cytokines (IL-6, IL-23, and IL-17) and chemokines (CCL5 and CXCL10) could have contributed to this increase in psoriasis severity." (PMID 35663991, 2022). "Previous studies have shown that quercetin and luteolin could inhibit the activation of the NF-κB pathway, reduce the levels of serum inflammatory factors such as TNF-α, IL-6, and IL-17, and significantly reduce the PASI score of IMQ-induced psoriasis mouse models." (PMID 35265149, 2022). "In this mechanism, stimulated keratinocytes function as the trigger of psoriasis by secreting cytokines, chemokines, and antimicrobial peptides (AMPs) to activate DCs which secret multiple proinflammatory cytokines such as TNF-α, interleukin (IL)-6, IL-12, IL-23 and IL-36." (PMID 36620087, 2022). "Many immune-derived cytokines and chemokines, including IL-17, IL-23, IL-6, C-X-C motif ligand-1 (CXCL-1), TNF-α, and p65, can drive inflammatory cell infiltration and an inflammation loop, thus regulating keratinocyte proliferation and leading to the development and maintenance of psoriasis." (PMID 35216231, 2022). "STAT3 signalling and IL-6 are closely related to the pathogenesis of psoriasis, and we hypothesized that KLHDC7B-DT might participate in regulating the inflammatory response and be involved in the pathogenesis of psoriasis." (PMID 35586566, 2022). "Consequently, we showed that the skin of IMQ-induced mice mimics the psoriatic characteristics with increased infiltration of inflammatory cells and increased levels of psoriasis-related cytokines and chemokines such as CXCL1, IL-25, IL-17A, IL-6, IL-1β, IL-36, CD4, and IFN-γ." (PMID 34641629, 2021). "As epidermal hyperplasia and inflammation are hallmarks of psoriasis, our new findings indicate that alantolactone can not only alleviate these skin lesions by inhibiting inflammation but also relieve epidermal hyperplasia by reducing the expression of TNF-α, IL-6, IL-1β, IL-8, IL-17A, and IL-23." (PMID 34202301, 2021). "Many previous studies revealed that psoriasis is an inflammatory disease, and patients with this disease may have higher serum levels of cytokines, such as tumour necrosis factor (TNF)-α, interferon (IFN)-γ, (interleukin (IL)-6, IL-8, IL-12, IL-17 and IL-18." (PMID 34290604, 2021). "Previous studies demonstrated that the pro-inflammatory cytokines, including TNF-α, IL-6, IL-1β, IL-17A, and IL-22 were up-regulated in psoriatic skin tissues and serum, and the IL-23/IL-17 axis was found to participate in the regulation of IMQ-induced psoriasis-like skin inflammation." (PMID 32515468, 2020).
psoriasis (continued). "The lack of a robust CRP signal in psoriasis and PsA is owed to the fact that interleukin (IL)-6, the essential stimulator of CRP, plays no critical role in these diseases, which is illustrated by the very limited therapeutic effect of IL-6 neutralization in psoriatic disease." (PMID 32051028, 2020). "The results determined that psoriatic keratinocyte exosomes could significantly promote the formation of NETs and subsequent expressions of IL-6, IL-8, and tumor necrosis factor-alpha (TNF-α) in neutrophils, which have been reported to play a critical role in psoriasis." (PMID 32993791, 2020). "The effects of IL‐38 on psoriasis development were demonstrated through IL‐38 injection into imiquimod‐induced psoriatic mice, showed down‐regulated levels of loricrin, CXCL8, CXCL20 and IL‐6, and ameliorated the manifestations, such as reduction of acanthosis and dermal inflammatory infiltrate." (PMID 33079487, 2020). "Also IFN-γ-induced, but not IL-22-induced IL-6 and IL-20, two psoriasis-related cytokines were inhibited by this drug." (PMID 30581877, 2018). "UVB irradiation inhibits IL-17A/TNF-α-induced IL-6, IL-8, and CXCL-1 production in HDFs by decreasing the expression of IL-17RA and IL-17RC on fibroblasts through TGF-β1/Smad3 signaling pathway, which reveals a new mechanism of the therapeutic action of UVB on psoriasis." (PMID 28217129, 2017). "Our results confirm that UVB irradiation inhibits IL-17A/TNF-α-induced IL-6, IL-8, and CXCL-1 production in HDFs by decreasing the expression of IL-17RA and IL-17RC on fibroblasts through TGF-β1/Smad3 pathway, which reveals a new mechanism of the therapeutic action of UVB on psoriasis." (PMID 28217129, 2017). "Furthermore, the proinflammatory cytokines involved in psoriasis pathogenesis—tumor necrosis factor (TNF) and interleukin (IL)-6—may also alter sleep physiology." (PMID 26745869, 2016). "So, focusing exclusively on the classical IL-6 signaling might not be an ideal treatment option in psoriasis." (PMID 26999594, 2016). "IL-6 was secreted at low levels with slightly more in psoriasis plaque T cells (0.09 versus 0.05 ng/ml, p = 0.18), while the soluble IL-1 receptor α (0.36 in ACD versus 0.28 ng/ml in psoriasis, p = 0.18) and TNF-α (4.5 versus 0.3 ng/ml, p = 0.18) were secreted in higher amounts by ACD T cells." (PMID 25058585, 2014). "Moreover, the cytokines IL6 and IL10 seem to be important in the development of psoriasis." (PMID 24069534, 2013). "In α2/β1 integrin double-transgenic mice, skin irritation led to a chronic condition resembling psoriasis with persistent hyperplasia, cutaneous influx of CD4+ and CD8+ T-lymphocytes and secretion of pro-inflammatory cytokines like TNF-α, IFN-γ, IL-1β and IL-6." (PMID 22590584, 2012). "In addition, HCRG21 reduced the expression levels of Tnf, Il1β, Il6, Il23a, and Il17a in both psoriatic scab and blood cells and inhibited protein production of IL-23-A and MDC levels compared to the values in the IMQ-induced groups, confirming positive anti-psoriasis dynamics." (PMID 41226679, 2025). "However, despite the lack of IL-6, KCs expressed various additional proinflammatory cytokines after the transient suppression of psoriasiform skin manifestation, delineating the ineffective treatment of psoriasis plaque by IL-6 blockage." (PMID 35563374, 2022). "Notably, IL-6 could cross selective barriers, and this trans-barrier signaling could be relevant in the crossing of the selective barrier of the muscle spindle in DOMS and in psoriasis disease progression." (PMID 36233237, 2022). "Furthermore, we confirmed that IFNγ-sEVs reduced psoriasis symptoms including thickness, erythema, and scales of skin lesions; exhausted Th17 cells, increased Th2 cells; and reduced enrichment of inflammatory cytokines such as IL-17A, IFN-γ, IL-6, and TNF-α in both spleen and skin lesions in vivo." (PMID 35359454, 2022).
psoriasis (continued). "This might be explained by the stronger systemic inflammation, which is proved by the higher levels of interleukin-6, CD16+ proinflammatory monocytes, osteoprotegerin, high-sensitive C-reactive protein, and vascular endothelial growth factor in psoriatic arthritis compared to psoriasis alone." (PMID 35415048, 2022). "The integration of metabolic and immune data indicated a molecular signature constituted by IL-6, IL1-ra, DMG, CCL4, Ile, Gly and IL-8, which could discriminate patients and healthy subjects and could represent a candidate tool in the diagnosis of new-onset psoriasis." (PMID 34006909, 2021). "However, a significant number of genes which may be induced by IL-23 or IL-22 such as GRO-1 (CXCL1), S100A7, S100A8, STAT3, IL-6, SCYA20 (CCL20), SCYA22 (macrophage-derived chemokine/CCL22), and β-defensin 2 have been identified in psoriasis microarray studies." (PMID 19884985, 2009). "Our results indicated that sodium orthovanadate treatment did not influence the P-STAT3 levels in HaCaT cells, compared to IL-6 and CYM treatment, suggesting that phosphatase was not involved in the S1PR3-mediated STAT3 activation in psoriasis." (PMID 39833165, 2025). "Salivary interleukins, including IL-1β, IL-6, TNF-α, and IL-17, offer significant results as non-invasive biomarkers for early detection, severity assessment, and treatment monitoring of psoriasis, effectively reflecting systemic inflammation." (PMID 40731810, 2025). "On the other hand, the ATCC12228EVs treatment decreased the mRNAs skin expression of VEGF-A, IL-6, KC, IL-17F, IL-23, and the IL-36 family members IL-36γ and IL-36R, compared to the IMQ-induced psoriasis skin mice with no EV treatment." (PMID 34884834, 2021). "In fact, IL-1 has the ability to stimulate MCs to produce IL-6, TNF, and IL-33 without degranulation, building a powerful proinflammatory network—an effect that increases with stress, which exacerbates psoriasis." (PMID 34360845, 2021). "Patients with psoriasis increased their lean (fat-free) mass and fat mass during treatment with anti-TNF-α and patients with RA treated with tocilizumab (an IL-6 inhibitor) for 1 year gained weight significantly, without change in fat mass." (PMID 32962676, 2020). "Patients with psoriasis and NAFLD were also more likely to have higher circulating levels of C-reactive protein, IL-6 and lower adiponectin levels than those without NAFLD." (PMID 26861300, 2016). "Additionally, diminished serum adiponectin levels in psoriasis patients, along with a negative correlation with BMI, TNF-α, and IL-6 levels, suggest a potential anti-inflammatory role in inhibiting adipocyte adipogenesis and Th17 cell-mediated inflammation." (PMID 38550599, 2024). "Interestingly, inhibition of IL-1, IL-6, or IFN-γ failed to achieve a significant clinical effect in psoriasis." (PMID 35313642, 2022). "In subgroup analysis, 10 % of patients in placebo, 14.3 % in metformin and 37.5 % of patients in pioglitazone subgroup had no decline or rather increase in the levels of IL-6 and TNF-α, consistent with the relapse of psoriasis in these patients in next 6 months." (PMID 27531132, 2016). "The significant induction of TNF-α increased IL-6, IL-8, EGF, HGF, TGF-α, epiregulin, and amphiregulin, but the increase in these cytokines and growth factors were not different among normal skin, uninvolved, and involved psoriasis." (PMID 20161853, 2009). "Also, in mice treated with the nanoemulsion gel, there was a significantly higher reduction of the Psoriasis Area and Severity Index (PASI) score without signs of skin irritation in any group, whereas the levels of IL‐6 and TNFα showed a maximum reduction in this treatment group." (PMID 40616290, 2025). "However, correlation analysis revealed that psoriasis presence did not significantly correlate with inflammatory biomarkers such as ROS (r = 0.08, p = 0.21), CRP (r = 0.11, p = 0.12), TNF-α (r = 0.09, p = 0.18), or IL-6 (r = 0.07, p = 0.23)." (PMID 41216079, 2025).
myeloma (654 papers, 2003 to 2026). "Numerous illnesses, including multiple myeloma, autoimmune disorders, and prostate cancer, are thought to be caused by the dysregulated production of IL6 and its receptor." (PMID 39129166, 2025). "Recent preclinical studies demonstrate that IL‐6/JAK‐STAT3 axis inhibition reduces myeloma cell viability while normalizing inflammation‐associated metabolic disturbances, supporting its therapeutic potential in precursor states." (PMID 41498034, 2025). "One example of possible inter-sublcone communication is in endogenous IL6 production by some myeloma cells where the IL6 production from the myeloma cells can have a self-stimulatory effect causing increased growth." (PMID 40002248, 2025). "As one example, interleukin-6 (IL-6) is implicated in the pathogenesis of multiple myeloma and also, in the development of symptoms such as fatigue." (PMID 39996862, 2025). "Raised IL-6 levels can be caused by the presence of MC, and it has been identified as the key growth and survival factor for myeloma cells." (PMID 36910651, 2023). "Production of cytokines, such as IL-6, by the myeloma cells, have not only been associated with the enrichment of anti-apoptotic factors in myeloma cells but also impaired dendritic cell function and T-cell activation." (PMID 36702834, 2023). "Myeloma-associated macrophages also are a major source of IL-6, IL-10 and IL-1β that help in tumor proliferation and survival." (PMID 35172851, 2022). "Alteminostat is a novel pan-HDAC inhibitor with significant in vitro growth inhibition of multiple myeloma cell lines, especially in reducing the secretion of interleukin 6, which is associated with the proliferation of myeloma cells." (PMID 34301270, 2021). "Consistent with previous reports, we found that CRS severity was also associated with the myeloma burden in bone marrow, and peak levels of serum IL-6 and ferritin." (PMID 34627333, 2021). "A region of 1210.71 kb in 7p15 with a gain of 28 copies contained the gene encoding for the IL6 cytokine that has been reported as a crucial factor for the proliferation and survival of myeloma cells." (PMID 33988237, 2021). "An abnormally high level of IL-6 in the serum of individuals with plasma cell dyscrasia is associated with advanced multiple myeloma." (PMID 31979357, 2020). "Expression of IL-6 is associated with increased HO-1 expression in multiple myeloma (MM) and high levels of both (IL-6 and HO-1) can be used as a marker of poor prognosis in MM." (PMID 33287312, 2020). "The mechanism underling the immunosuppressive activity of IL-6 in multiple myeloma is complex and still poorly understood." (PMID 30154786, 2018). "In multiple myeloma, the expression of PD-L1 can be induced by IL-6, and higher levels of PD-L1 expression are associated with increased anti-apoptotic ability and more aggressive behavior of myeloma cells." (PMID 31548533, 2017). "IL-6 has been implicated as an autocrine promoter of cancer growth for various human cancers such as biliary tract epithelial cancers, multiple myeloma, and prostate cancer." (PMID 27034885, 2016). "The evidence that Notch signaling positively controls IL-6 in the myeloma-associated BM makes this pathway a key mediator of tumor-directed reprogramming of the bone niche." (PMID 27463014, 2016). "High levels of serum IL-6 produced by neoplastic plasma cells and bone marrow stromal cells in multiple myeloma are associated with poor prognosis." (PMID 27500125, 2016). "Polymorphisms in the IL6 promoter region have been implicated in susceptibility to carotid atherosclerosis, multiple myeloma, and juvenile chronic arthritis." (PMID 25127106, 2014). "IL-6 causes the growth of myeloma cells inthe JAK/STAT pathway by increasing expressionof myeloid-cell-leukemia (Mcl-1)." (PMID 24567933, 2014). "IL-6, whose expression is regulated by NF-κB, has been implicated in the oncogenesis process by inducing proliferation of multiple myeloma cells." (PMID 23117246, 2013).